IFITM3 (interferon induced transmembrane protein 3)
Diseases named in the same sentence as IFITM3 in open-access papers (continued):
Sharing a sentence is not in itself a finding about the gene and the disease.
lymphopenia (3 papers, 2017 to 2022). Reduction in the number of lymphocytes. "Instead, IFITM3 promoted antiviral cellular immunity through the restriction of virus-induced lymphopenia, apoptosis-independent NK cell death, and loss of T cells." (PMID 28240600, 2017). "Further, our data suggest that IL-6–induced, apoptosis-independent lymphocyte death was associated with lymphopenia in MCMV-infected Ifitm3–/– mice." (PMID 28240600, 2017). "Collectively, these data implied that apoptosis-independent cell death was a significant factor underpinning lymphopenia in MCMV-infected Ifitm3–/– mice." (PMID 28240600, 2017). "We found that MCMV-infected Ifitm3–/– mice had exacerbated systemic lymphopenia and a concomitant elevation of circulating granulocytes during MCMV infection." (PMID 28240600, 2017). "Ifitm3–/–mice exhibit exacerbated lymphopenia and increased leukocyte death during MCMV infection." (PMID 28240600, 2017). "Circulating blood platelets and red blood cells were not reduced in Ifitm3–/– mice, suggesting that lymphopenia was not a consequence of generalized bone marrow suppression." (PMID 28240600, 2017).
Obesity (3 papers, 2015 to 2022). Accumulation of substantial excess body fat. "Interestingly, ADAM17 and IFITM3 mRNA levels were maximal in the patients that became critically ill during hospitalization (one-way ANOVA, post-hoc analysis) and in patients with obesity (with BMI > 30) (one-way ANOVA, post-hoc analysis)." (PMID 36009555, 2022). "ADAM17, IFITM3, IL6 and IFNE were more highly expressed in PBCs of patients with obesity." (PMID 36009555, 2022). "Thus, expression patterns of three genes (IFITM3, ADAM17, IFNE) in PBCs at the time of hospital admission marked both disease evolution severity and obesity status, especially in male patients." (PMID 36009555, 2022).
pulmonary TB (3 papers, 2020 to 2023). "Another functional polymorphism rs3888188, showed that peripheral-blood mononuclear cells carrying GG genotype had reduced IFITM3 mRNA level compared to those with TT or GT genotype, which predisposes toward pulmonary tuberculosis in Iranian and Han Chinese populations." (PMID 33101356, 2020). "The top performing single biomarkers for pulmonary TB versus controls were CALCOCO2, SAMD9L, GBP1, IFITM3, IFIT3 and SNX10." (PMID 35720382, 2022).
respiratory infection (3 papers, 2016 to 2022). "One of the most respiratory infection relevant being IFN induced transmembrane protein 3 (IFITM3), an antiviral effector exerting potent activity to inactivate influenza virus." (PMID 33187194, 2020). "The IFITM3 rs12252 variant was associated with respiratory infection hospitalization but not specifically in patients infected with Influenza A(H1N1)pdm09." (PMID 27351739, 2016). "However, bulk IFITM1 and IFITM3 mRNA expression dynamics and their correlation with clinical outcomes have not been extensively addressed in patients with respiratory infections." (PMID 35708622, 2022).
amyloid (2 papers, 2020 to 2022). "In 5xFAD transgenic mice, which express five familial AD mutations and recapitulate features of AD amyloid pathology, IFITM3 levels increased with age, whereas PS1 and NCT levels remained relatively constant." (PMID 33183335, 2020). "Together, these findings provide a novel foundation for the role of microglial Ifitm3 expression in response to inflammatory stress and amyloidosis in the brain." (PMID 36012150, 2022). "Targeting IFITM3 should be explored as an AD therapeutic strategy for reducing amyloid deposition." (PMID 33183335, 2020). "Since we found a significant induction of IFITM3 in response to various inflammatory stressors (LPS, TNFα, and IFNγ) and recent findings suggest a novel role of IFITM3 in amyloid pathology, we sought to examine whether amyloid peptide could induce IFITM3 expression in primary microglia." (PMID 36012150, 2022).
autism (2 papers, 2018 to 2022). Persistent deficits in social interaction and communication and interaction as well as a markedly restricted repertoire of activity and interest as well as repetitive patterns of behavior. "IFITM3 has also been implicated in another disorder defined by immune-related risk during neurodevelopment, namely autism." (PMID 34789849, 2022).
bacterial sepsis (2 papers, 2022 to 2025). "Interferon-induced transmembrane protein 3 (IFITM3) expression, which is upregulated by systemic interferons, is increased in platelets from bacterial sepsis patients and is associated with increased platelet reactivity." (PMID 41303674, 2025). "Given our clinical findings in septic patients, we assessed whether experimental bacterial sepsis induces platelet Ifitm3 expression and increases platelet reactivity using a murine polymicrobial cecal-ligation and puncture (CLP) model." (PMID 36194487, 2022). "As IFITM3 can regulate endocytosis and thrombosis is a complication of bacterial sepsis, we asked whether increased IFITM3 also increased the endocytosis of procoagulant platelet proteins during septic conditions." (PMID 36194487, 2022).
bladder cancer (2 papers, 2021 to 2024). "Our data is consistent with a prior study by Cai that high-IFITM3 expression correlated with high hypoxia score in the bladder cancer using bio-informatic method." (PMID 38218875, 2024). "Next, correlations between IFITM3 and immunological features in the bladder cancer (BLCA) tumor microenvironment (TME) were assessed." (PMID 34456915, 2021). "In this study, a pancancer analysis of the expression and immunological characteristics of IFITM3 was first performed, and the results revealed that IFITM3 was highly correlated with immunological factors in most cancers, but the tightest correlation was found in bladder cancer (BLCA)." (PMID 34456915, 2021).
brain injury (2 papers, 2023 to 2024). Acute and chronic (see also brain INJURIES, CHRONIC) injuries to the brain, including the cerebral hemispheres, CEREBELLUM, and brain STEM. "Second, future studies will be needed to clarify whether IFITM3 has the capacity to modulate microglial phenotype in conditions of chronic ischemic brain injury." (PMID 36994418, 2023). "Secondly, future studies are needed to clarify whether IFN-β signaling molecules, such as IFITM3, have the ability to regulate the microglia phenotype following CCH-induced brain injury." (PMID 37917300, 2024).
Cirrhosis (2 papers, 2021 to 2023). A chronic disorder of the liver in which liver tissue becomes scarred and is partially replaced by regenerative nodules and fibrotic tissue resulting in loss of liver function. "DNA sequencing was applied for detection of IFITM3 rs 12252-CC and IFITM3 protein level was measured by ELISA to 50 patients with HCC with cirrhosis and 50 with Hepatitis C virus infection." (PMID 37353775, 2023). "RhoA, CTNNB1 and SPINK1 showed a significant 3.3-, 3.2- and 3.18-folds upregulation, respectively, in HCC patients compared to cirrhosis patients while IFITM3 and SERPIND1 presented a 2.24-fold change." (PMID 34469466, 2021). "Our suggested mRNA signature including CTNNB1, RhoA, SPINK1, IFITM3 and SERPIND1, alongside other platelets mRNA, can be utilized as biomarkers for comparison of hepatic cirrhosis and HCC." (PMID 34469466, 2021). "Therefore, the 2.24-fold increased expression of IFITM3 in HCC as compared to cirrhosis, demonstrated in our study, can also be attributed to its antiviral signaling and inflammation which are the hallmarks of tumor progression in cirrhosis and HCC cases having viral etiology." (PMID 34469466, 2021).
Cognitive impairment (2 papers, 2021 to 2023). Abnormal cognition is characterized by deficits in thinking, reasoning, or remembering. "Overexpression of IFITM3 resulted in elevated anxiety levels and long-term learning and memory dysfunction, completely abolished the therapeutic effect of rhBNP on cognitive impairment in septic mice, and induced an increase in the number of neuronal apoptosis in the hippocampal CA1 region." (PMID 37602193, 2023).
endometriosis (2 papers, 2015 to 2024). The growth of functional endometrial tissue in anatomic sites outside the uterine body. "A homogeneous cytoplasm distribution of IFITM3 immunolabelling was found in isolated cells and clusters of cells in all endometriosis samples." (PMID 26446766, 2015). "Nevertheless, the presence of ovarian germ line stem cells as contributors to endometriosis progression remains to be further studied through functional analysis in isolated DDX4/IFITM3-positive cells." (PMID 26446766, 2015). "The identification of germ cell-specific proteins DDX4 and IFITM3 provides the first evidence of ovarian-sourced cells in ovarian endometriotic lesions and opens up new directions towards understanding the still confusing pathogenesis of endometriosis." (PMID 26446766, 2015). "In this context, up regulation of DDX4 and IFITM3 proteins in ovarian-sourced stem cells, as well as OCT4 in eMSC, could correlate with the molecular pathway towards the malignant forms of the endometriosis lesion." (PMID 26446766, 2015). "However, normal endometrial tissue is negative for IFITM3, which is expressed in ovarian endometriosis lesions, so IFITM3 may promote the development of endometriosis." (PMID 38239300, 2024).
esophageal squamous cell carcinoma (2 papers, 2015 to 2021). Esophageal squamous cell carcinoma (ESCC) is a type of esophageal carcinoma (EC) that can affect any part of the esophagus, but is usually located in the upper or middle third. "In esophageal squamous cell carcinoma, patients with high expression of IFITM3 are more likely to develop lymph node metastasis after surgery." (PMID 34659578, 2021). "Our research aimed to investigate the expression of IFITM3 in pathological N0 (pN0) esophageal squamous cell carcinoma (ESCC) and its relationship with lymph node metastatic recurrence." (PMID 26539332, 2015).
glomerulonephritis (2 papers, 2017 to 2024). A renal disorder characterized by damage in the glomeruli. "Our ABBA analysis allowed us to propose a new role for Ifitm3 in the pathogenesis of glomerulonephritis via a mechanism involving promoter hypermethylation that is associated with Ifitm3 repression in the rat strain susceptible to glomerulonephritis." (PMID 28213474, 2017). "While a role for IFN-signaling genes in autoimmune disease has been previously suggested, our findings on methylation alteration of the Ifitm3 gene associated with glomerulonephritis in the rat might suggest future directions for the study of the pathogenesis, and to develop treatments of CRGN." (PMID 28213474, 2017). "This was confirmed by ChIP-seq and RNA-seq analyses, showing differential transcription factor binding at the Ifitm3 promoter by JunD (an established determinant of glomerulonephritis), and a consistent change in Ifitm3 expression." (PMID 28213474, 2017). "Therefore, our ABBA analysis of WGBS data in primary macrophages from a rat model of CRGN allowed us to propose an AP-1-mediated role for Ifitm3 in glomerulonephritis." (PMID 28213474, 2017).
herpesvirus infection (2 papers, 2017 to 2021). "As reported, inhibition of LSD1 restricts herpesvirus infection, shedding, and recurrence, through epigenetic suppression of viral genomes, while LSD1 represses influenza A virus infection by erasing monomethylation on lysine 88 of interferon induced transmembrane protein 3 (IFITM3)." (PMID 34529741, 2021).
liver cancer (2 papers, 2021 to 2025). An epithelial or non-epithelial malignant neoplasm that arises from the liver. "First, we found that IFITM3 is highly expressed in liver cancer tissues through the GEPIA2 database." (PMID 34659578, 2021). "Our previous studies have shown IFITM3 as a direct target of miR-29a and an important gene regulating the development of liver cancer." (PMID 34659578, 2021). "In liver cancer, IFITM3 can promote tumor metastasis, and patients with high expression of IFITM3 have a relatively poor prognosis." (PMID 34659578, 2021). "The objective of this study was to investigate the regulatory relationship between TUG1, miR-29a, and IFITM3 in human liver cancer." (PMID 34659578, 2021). "It acts as an oncogene and competitively binds to miR-29a as a ceRNA to regulate IFITM3, which in turn affects the development and progression of liver cancer." (PMID 34659578, 2021). "Previous studies have implicated the NF-κB signaling pathway in promoting tumor cell proliferation, while c-myc has been reported to correlate positively with IFITM3 expression in liver cancer cells though this relationship has not been established in AML." (PMID 40969269, 2025).
microcephaly (2 papers, 2016 to 2017). A congenital or acquired developmental disorder in which the circumference of the head is smaller than normal for the person's age and sex. "However, when we tested Zika virus, the recently re-emerged arbovirus associated with microcephaly, we found that the levels of IFITM3-K88me1 were reduced upon infection even though the expression levels of IFITM3 increased." (PMID 29281729, 2017). "One of the novel interactors predicted for IFITM3 is DEAF1, mutations in which has been linked to white matter disease, microcephaly and syndromic intellectual diability using whole exome sequencing." (PMID 29333229, 2016).
myocarditis (2 papers, 2025). Myocarditis is a condition that is characterized by inflammation of the heart muscle (myocardium). "Variants in interferon-induced transmembrane protein-3 have been associated with influenza-related myocarditis, and animal studies have demonstrated associations between autoimmune myocarditis and HLA-DQ8 expression." (PMID 41527630, 2025).
ovarian endometriosis (2 papers, 2015 to 2024). A non-neoplastic disorder characterized by the growth of endometrial tissue in the ovaries. "We identified DDX4 and IFITM3 proteins in isolated and clusters of cells in ovarian endometriosis lesions." (PMID 26446766, 2015). "The expression of IFITM3 in ovarian endometriosis lesions was confirmed by RT-PCR and normal endometrial tissues were negative for IFITM3-mRNA." (PMID 26446766, 2015). "Ten paraffin-embedded ovarian endometriosis samples were screened for germ cell-specific proteins DDX4 (VASA) and IFITM3, and its relation with stem cell marker OCT4, proliferation marker PCNA and estrogen receptor alpha (ESR1), by immunohistochemistry, immunofluorescence and PCR." (PMID 26446766, 2015).
periodontitis (2 papers, 2022 to 2025). An acute or chronic inflammatory process that affects the tissues that surround and support the teeth. "Periodontitis induced an 8-fold higher expression of the IFITM3 gene, while the artificial overexpression of IFITMs blocks SARS-CoV-2 infection." (PMID 36366382, 2022). "Other than ACE2, BMAL1, CD147, FURIN, and TMPRSS2, more genes, including CD26(DPP4), IFITM3, HLA, ABO, SLC6A20, GSTT1-M1, and DBP, have also been implicated in SARS-CoV-2 and periodontitis." (PMID 36366382, 2022). "Animal study to investigate whether Pg-induced periodontitis triggers type I interferon responses and activates the IFITM3–Aβ axis, thereby contributing to AD–like pathology." (PMID 41170438, 2025).
primary Sjögren’s syndrome (2 papers, 2015 to 2017). "In addition, DNA methylation alterations in IFN-related genes, including Ifitm3, have been previously observed and proposed to contribute to the pathogenesis of other autoimmune diseases such as primary Sjögren’s syndrome." (PMID 28213474, 2017).
tuberculosis (2 papers, 2013 to 2021). A chronic, recurrent infection caused by the bacterium Mycobacterium tuberculosis. "IFITM3 has also been implicated in a wide range of diseases such as cancer metastasis, tuberculosis susceptibility, and ulcerative colitis." (PMID 34404769, 2021). "One possible mechanism by which IFITM3 expression levels may modulate susceptibility to TB is a reduced capacity to eliminate M. tuberculosis in phagolysosome." (PMID 23874452, 2013). "Because IFITM3 plays a pivotal role in IFN-γ signaling and successful immunity against M. tuberculosis requires strong IFN-γ signaling, we further hypothesized that the TB-susceptible rs3888188 G allele could lead to reduced IFITM3 transcription." (PMID 23874452, 2013).
adenomyosis (1 paper, 2024). The growth of endometrial tissue inside the muscular wall of the uterine corpus. "Further studies are also required to validate the underlying molecular mechanism between COX-2, IFITM3, SFRP4 and adenomyosis." (PMID 38239300, 2024). "The results of this study also showed that IFITM3 expression in ectopic endometrium of adenomyosis was positively correlated with COX-2." (PMID 38239300, 2024). "IFITM3 was mainly expressed in mesenchymal cells of ectopic endometrium in adenomyosis, and to a lesser extent in glandular cells and the myometrium." (PMID 38239300, 2024). "The findings of this study also confirmed that IFITM3 expression in adenomyosis tissue was correlated with dysmenorrhea symptoms." (PMID 38239300, 2024). "IFITM3 may influence the development of adenomyosis and be a potential molecular target for the treatment of dysmenorrhea." (PMID 38239300, 2024). "COX-2, IFITM3, and SFRP4 are significantly associated with the degree of dysmenorrhea, and they may be potential molecular targets for the treatment of dysmenorrhea in patients with adenomyosis." (PMID 38239300, 2024). "In ectopic endometrium of adenomyosis, the expression levels of COX-2 were positively correlated with the expressions of WBP2, IFITM3, and SFRP4 (r = 0.536, P < 0.01; r = 0.591, P < 0.01; r = 0.533, P < 0.01)." (PMID 38239300, 2024). "This study demonstrated that COX-2, WBP2, IFITM3, and SRFP4 may be involved in the pathogenesis of adenomyosis." (PMID 38239300, 2024). "COX-2, IFITM3, and SFRP4 may serve as potential molecular biomarkers or therapeutic targets in dysmenorrhea in patients with early adenomyosis." (PMID 38239300, 2024). "COX-2, IFITM3, SFRP4, and WBP2 may be involved in the pathogenesis of adenomyosis." (PMID 38239300, 2024). "Thus, the expression of COX-2, WBP2, IFITM3, and SFRP4 did not correlate significantly with menstrual flow and volume in adenomyosis." (PMID 38239300, 2024).
allergic asthma (1 paper, 2023). A asthma with a basis in a pathological type I hypersensitivity reaction. "Interferon-induced transmembrane protein 3 (IFITM3), while unexplored in human allergic asthma, has been shown to drive and exacerbate Th2-cell responses in mouse studies, with genome studies linking IFITM2/3 variants to basophil counts and lung function." (PMID 38062491, 2023).
allergic rhinitis (1 paper, 2024). Inflammation of the nasal mucous membranes caused by an IgE-mediated response to external allergens. "Previous literature has reported that IFITM3 overexpression can increase the STAT1 expression, and STAT1 is involved in the pathogenesis of SEA‐induced allergic rhinitis and IgE production, but the exact mechanism remains unclear." (PMID 39412083, 2024).
Anxiety (1 paper, 2023). Intense feelings of nervousness, tension, or panic often arise in response to interpersonal stresses. "It is suggested that overexpression of IFITM3 aggravates the exploration ability of septic mice and increases their anxiety level, which completely abolishes the therapeutic effect of rhBNP." (PMID 37602193, 2023).
Arterial thrombosis (1 paper, 2022). The formation of a blood clot inside an artery. "Under inflammatory stress, increased IFITM3 expression was associated with greater arterial thrombosis and mortality from pulmonary thromboembolism." (PMID 36194487, 2022).
Arthritis (1 paper, 2017). Inflammation of a joint. "Although Ifitm3 has recently been shown to be sufficient in vivo to delay chikungunya virus-induced arthritis, the possible contribution of osteoblasts in that process was not examined." (PMID 28880886, 2017).